PDPN (podoplanin)
Diseases named in the same sentence as PDPN in open-access papers (continued):
Sharing a sentence is not in itself a finding about the gene and the disease.
meningeal tumors (1 paper, 2017). "Additionally, FOS, MYC, and PDPN have been shown to be overexpressed specifically in meningeal tumors." (PMID 29073243, 2017).
mesenchymal neoplasms (1 paper, 2025). "On the other hand, podoplanin (D2-40) expression has been reported in about 25–30% of PCLs and some germinal and mesenchymal neoplasms." (PMID 39941848, 2025).
metastatic melanoma (1 paper, 2012). A melanoma that has spread from its primary site to another anatomic site. "PDPN expression was drastically increased in primary and metastatic melanoma specimens from every patient that we examined." (PMID 22844530, 2012).
mycosis fungoides (1 paper, 2022). Classical mycosis fungoides is the most common type of mycosis fungoides (MF), a form of cutaneous T-cell lymphoma, and is characterized by slow progression from patches to more infiltrated plaques and eventually to tumors. "In mycosis fungoides, podoplanin is expressed in the basal cell layer of the epidermis, the malignant lymphocytes in epidermis and dermis, and the lymphatic vessels in dermis." (PMID 35163233, 2022). "There is a significant positive correlation between the intensity of podoplanin expression in the basal cell layer of the epidermis, malignant lymphocytes, and lymphatic vessels and the TNMB staging of mycosis fungoides." (PMID 35163233, 2022).
myeloma (1 paper, 2018). "However, several hybridoma cells produced by fusing spleen cells from the mice and myeloma cells could not recognize PDPN in sections from paraffin-fixed normal rectal tissues even after six times of cell fusion." (PMID 29976954, 2018).
nasal polyps (1 paper, 2018). "Furthermore, podoplanin-positive lymphatics were increased in the nasal polyps of patients with ECRS compared to the control nasal mucosa." (PMID 29951134, 2018).
non-melanoma skin carcinoma (1 paper, 2022). "The critical role of podoplanin in tumor lymphangiogenesis is allowing lymphatic spread and metastasis of aggressive non-melanoma skin cancer." (PMID 36505148, 2022).
Obesity (1 paper, 2015). Accumulation of substantial excess body fat. "We observed that increased adipocyte size (a hallmark of obesity) was directly associated with leptin expression, angiogenesis (CD31) and lymphangiogenesis (podoplanin); however, these parameters were associated with nodal metastasis only in peritumoral but not distal adipose tissue of patients." (PMID 25857300, 2015).
odontogenic cyst (1 paper, 2024). A cyst in the jaw that arises from tissues of tooth development. "Regarding DC and orthokeratinized odontogenic cyst, merely cases of inflammation were positive for podoplanin." (PMID 38962078, 2024). "Future studies are suggested to investigate the role of inflammation in the podoplanin expression in odontogenic cysts than dental follicles as a control group, and assesse the podoplanin expression in other odontogenic lesions." (PMID 38962078, 2024). "On the other hand, lymphangiogenesis affects the biological behavior of lesions, the present study investigated the podoplanin immunohistochemical expression in OKCs compared to DCs as two biologically different odontogenic cysts." (PMID 38962078, 2024). "They observed the strong expression of podoplanin in OKC compared to orthokeratinized odontogenic cyst and emphasized that podoplanin plays a definite role in tumor invasiveness." (PMID 38962078, 2024). "In other words, the rate of mitotic activity and podoplanin expression in the cytoplasm and membrane of odontogenic epithelial cells was significantly higher in OKC than in orthokeratinized odontogenic cyst." (PMID 38962078, 2024).
ovarian tumors (1 paper, 2024). "Immunohistochemical staining of serial tumor sections revealed the expression of mesothelial markers (PDPN and calretinin) in CAFs located in areas surrounding tumor cells in primary ovarian tumors and secondary peritoneal metastases." (PMID 39123425, 2024).
Paget disease (1 paper, 2020). A malignant neoplasm composed of large cells with large nuclei, prominent nucleoli, and abundant pale cytoplasm (Paget cells). "In this study, a dramatic increase in the number of CD34-positive blood vessels, with a minor proportion of podoplanin (D2–40)-positive lymphatic vessels, was observed in the Paget disease group." (PMID 32527320, 2020). "Indeed, our results demonstrated a significant increase in the average LVD in Paget disease and its positive correlation with bFGF expression; however, podoplanin (D2–40)-positive lymphatic vessels comprised a minor proportion of the vessels compared with the CD34-positive blood vessels." (PMID 32527320, 2020).
papilloma (1 paper, 2020). A benign epithelial neoplasm that projects above the surrounding epithelial surface and consists of villous or arborescent outgrowths of fibrovascular stroma. "Western-blot analysis showed that while podoplanin was undetectable from non-tumorigenic MCA3D and papilloma PB cells, it was co-expressed with CD44v isoforms of 100–180 kDa in SCC cell lines PDV and B9." (PMID 33003440, 2020).
Peritoneal Fibrosis (1 paper, 2012). Disorder characterized by a wide range of structural changes in PERITONEUM, resulting from fibrogenic or inflammatory processes. "Furthermore, in patients on PD with simple peritoneal fibrosis, diffuse accumulation of podoplanin positive myofibroblasts was rarely detected." (PMID 23300922, 2012).
Pleural effusion (1 paper, 2016). The presence of an excessive amount of fluid in the pleural cavity. "Podoplanin+MPs and mucin 1+MPs were found in pleural effusions of both cancer and benign origin." (PMID 26689993, 2016).
pneumococcal pneumonia (1 paper, 2022). A febrile disease caused by STREPTOCOCCUS PNEUMONIAE. "Deletion of UGRP1 or blocking UGRP1 interaction with PDPN protected mice against S. pneumoniae‐induced severe pneumococcal pneumonia, and activating RhoA with agonist in UGRP1‐deficient mice restored the reduced IL‐6 production." (PMID 35652821, 2022).
postpartum hemorrhage (1 paper, 2022). Hemorrhage defined as a blood loss in excess of 500 mL after vaginal delivery or more than 1000 mL after a cesarean delivery. "Eight genes were associated with hemostatic pathways (SELL, CAPZB, SLC16A3, PDPN, TNFRSF10B, SH2B2, NFE2, and TNFRSF10D), which provided novel insights for the prevention and management of postpartum hemorrhage." (PMID 35836580, 2022).
Prostate tumor (1 paper, 2014). "Prostate tumor xenografts displayed increased vascularization, enlarged podoplanin-positive lymphatic vessels and invasive margins." (PMID 24885350, 2014).
Protein-losing enteropathy (1 paper, 2025). Abnormal loss of protein from the digestive tract related to excessive leakage of plasma proteins into the lumen of the gastrointestinal tract. "We aimed to investigate the relationship between the Podoplanin expression in jejunal villi and the pathogenesis of congenital protein-losing enteropathy (PLE), using the Podoplanin heterozygous knock-out (Pdpn-het KO) mice and aspirin-induced inflammation of the jejunum." (PMID 40737946, 2025).
rectum adenocarcinoma (1 paper, 2025). An adenocarcinoma arising from the rectum. "The higher expression of PDPN in CRC versus normal tissues was further confirmed also at molecular level by analyzing GTex/TCGA colon and rectum adenocarcinoma public datasets." (PMID 40842027, 2025).
rotator cuff tears (1 paper, 2021). "Fibroblasts isolated from rotator cuff tears demonstrate increased expression of the activation markers PDPN, VCAM1 and CD248.." (PMID 35096791, 2021).
squamous cell carcinomas of the skin (1 paper, 2016). "Another protein that accelerates cell motility and invasion of keratinocytes, is Podoplanin, a mucin-type transmembrane glycoprotein that is up-regulated in human squamous cell carcinomas of the skin." (PMID 27732959, 2016).
squamous cell carcinomas of the vulva (1 paper, 2025). "In the present study, we systematically examined the clinical relevance and the prognostic role of both podoplanin-expressing tumor cells as well as podoplanin expressing CAFs in HPV-associated and HPV-independent squamous cell carcinomas of the vulva." (PMID 40542163, 2025). "Although the immunohistochemical expression of the transmembrane sialoglycoprotein podoplanin (D2-40) has been repeatedly reported as a factor of prognosis in various tumor entities—its potential prognostic relevance in squamous cell carcinomas of the vulva remains to be evaluated." (PMID 40542163, 2025).
supraglottic tumours (1 paper, 2010). "Podoplanin expression was also significantly more frequent in glottic tumours, which are generally smaller and detected at an earlier stage than supraglottic tumours." (PMID 20196862, 2010).
thoracic tumors (1 paper, 2025). "In this study, we analyzed the PDPN immunostaining profiles of malignant thoracic tumors diagnosed at our institution, including EMPM (n = 11), LAC (n = 100), and LSCC (n = 23)." (PMID 40428290, 2025). "Based on our results, we prepared a workflow for the differential diagnosis of malignant thoracic tumors using PDPN immunohistochemistry and subsequent FE-SEM analysis of PDPN-positive sites using the NanoSuit-CLEM method." (PMID 40428290, 2025).
Thrombocytopenia (1 paper, 2019). A reduction in the number of circulating thrombocytes. "The transgenic overexpression of soluble PDPN-Fc in mouse skin provoked platelet activation via CLEC-2, causing disseminated intravascular coagulation and thrombocytopenia." (PMID 30736372, 2019). "Podoplanin was also found to mediate platelet aggregation and thrombocytopenia induced by umbilical cord mesenchymal stem cells infused into mice via the tail vein." (PMID 30736372, 2019). "In this regard, Cueni and coworkers reported that targeted expression of the podoplanin ectodomain in the epidermis of transgenic mice allowed entrance of the protein into the blood circulation and induced microthrombi and thrombocytopenia, with occasional fatal hemorrhages." (PMID 30736372, 2019).
thymic carcinoma (1 paper, 2020). Thymic carcinoma (TC) is a type of thymic epithelial neoplasm characterized by a high malignant potential. "Ten markers, namely Podoplanin, Glut-1, Muc-1, Egfr, Igf1r, c-Jun, and n-Ras, from ten articles that included 748 cases of thymoma and 280 cases of thymic carcinoma were selected." (PMID 32993581, 2020).
trichoepithelioma (1 paper, 2021). "BCC shows a stronger and diffused Bcl-2 and CD10 expression more frequently than trichoepithelioma, while the latter is positive for CK20 and podoplanin (D2-40) in the peripheral tumor nests." (PMID 34639065, 2021).
uveal melanoma (1 paper, 2021). A melanoma derived from melanocytes of the uveal tract. "Podoplanin and LYVE-1 are also implicated in uveal melanoma." (PMID 33669860, 2021).
viral hepatitis (1 paper, 2023). An acute or chronic inflammation of the liver parenchyma caused by viruses. "Systemic and local inflammation caused by viral hepatitis and increased portal pressure can damage vascular endothelial cells, allowing circulating platelet CLEC-2 to interact with subendothelial podoplanin and possibly with some other unidentified ligands." (PMID 37720512, 2023).
viral myocarditis (1 paper, 2024). Myocarditis that is caused by an infection with a viral agent. "Th17 cells play a crucial role in the development of TLSs by secreting cytokines, such as IL-17 and IL-22.147,551 IL-17A+ PDPN+ T cells are present within TLSs in the myocardial tissue of viral myocarditis." (PMID 39198425, 2024).
vulvar carcinoma (1 paper, 2025). "In the present study, we evaluated 68 patients with primary vulvar carcinomas (VC) and analyzed the cytoplasmic/membranous immunohistochemical expression of podoplanin in viable tumor cells and cancer-associated fibroblasts (CAFs) within the adjacent peritumoral stroma." (PMID 40542163, 2025). "In the present study, we systematically examined the immunohistochemical expression of podoplanin as an easily applicable and broadly available biomarker in not only viable vulvar carcinoma cells but also peritumoral fibroblasts." (PMID 40542163, 2025).
tumor (637 papers, 2006 to 2026). "PDPN-expression was linked to tumour cell collagen-expression and suppression of interferon-signalling, features associated with an immune-cold microenvironment." (PMID 41957138, 2026). "The strong diagnostic performance and independent predictive value observed in our cohort further support PDPN as a biomarker linked to tumor progression and adverse biological features." (PMID 41594182, 2026). "Overexpression of PDPN has been shown to be associated with aggressive tumor behavior and poor clinical outcomes in OC, supporting its role as a prognostic biomarker." (PMID 41594182, 2026). "We also demonstrated specific spreading of T cells decorated with anti-podoplanin on tumor associated lymphatics enriched with this surface antigen." (PMID 39995660, 2025). "The interaction between CLEC-2 and podoplanin promotes platelet aggregation induced by tumor cells and has been implicated in tumor metastasis." (PMID 41209555, 2025). "Others, for example, podoplanin (PDPN), have been associated with improved prognosis in CRC, with PDPN-positive CAFs being related to decreased depth of tumor invasion, and their location is in the tumor center rather than at the invasion front." (PMID 41450913, 2025). "Cluster analysis using VOSviewer identified PDPN-associated modules encompassing platelet aggregation, tumor microenvironment, inflammation, lymphatic metastasis, and CD8+ T lymphocyte biology." (PMID 41573582, 2025). "We chose as a model cell surface antigen podoplanin, a mucin-type transmembranal protein enriched both on tumor associated lymphatics and cancer associated fibroblasts." (PMID 39995660, 2025). "Nevertheless, a fraction of the tumor injected T cells decorated with biotin anti-podoplanin mAb was found to interact with tumor-associated lymphatic vessels." (PMID 39995660, 2025). "For instance, PDPN-expressing cancer-associated fibroblasts (PDPN+ CAFs) are associated with an immunosuppressive tumor microenvironment characterized by increased CD204+ tumor-associated macrophage infiltration, while CD8+ and FOXP3+ TILs did not." (PMID 41573582, 2025). "As a transmembrane protein extensively expressed in stromal cells and tumor cells, PDPN has been documented to modulate platelet activation and tumor‐associated thrombosis." (PMID 38470096, 2024). "Given that SPP1+macrophages are associated with poorer clinical outcomes in cancers 32 and PDPN is related to tumor relapse 33, these two subsets were annotated as TAMs." (PMID 39239507, 2024). "The elevated expression of PDPN is also observed in cancer-associated fibroblasts (CAFs), a principal constituent of the tumor microenvironment (TME)." (PMID 39594582, 2024). "Overexpression of PDPN is associated with the progression of various solid tumors, and plays an important roles in the tumor microenvironment by regulating the immune system." (PMID 38167452, 2024). "PDPN-positive CAFs are also associated with an immunosuppressive tumor microenvironment, characterized by high levels of CD204+ tumor-associated macrophages and a low CD8/FOXP3 T-cell ratio." (PMID 40741180, 2024). "The intensity of PDPN staining was associated with higher levels of intravascular platelet aggregates in tumor specimens." (PMID 39682237, 2024). "Consistent with the flow cytometry profiles, the results of this study showed that more WT platelets were associated with PDPN + tumour cells than was observed with the other three groups." (PMID 38561690, 2024). "PDPN has been shown to enhance the formation of metastatic foci, tumor progression, and cancer-associated thrombosis in animal studies without direct effects on tumor growth." (PMID 39451677, 2024). "CCL21 serves as a potent chemoattractant in the tumor microenvironment and connects with PDPN-carrying cancer-associated fibroblasts (CAFs), aiding in tumors’ immune evasion." (PMID 39682237, 2024).
tumor (continued). "In human breast cancer, high aSMA or PDGFRb+ myofibroblast infiltration was associated with poor patient prognosis, and high PDPN expression is associated with higher tumor grade." (PMID 38525245, 2024). "Podoplanin (PDPN), also known as aggrus, encodes a glycoprotein associated with cell migration and adhesion and is over-expressed in a variety of tumor cells." (PMID 36937386, 2023). "TGF-β inhibition, on the other hand, strongly reduces PDPN-induced EMT and metastasis in mice injected with tumor cells, implying that podoplanin causes tumor metastasis by boosting platelet-derived TGF-β." (PMID 37298230, 2023). "The PDPN-deficient CD8+ tumor-infiltrating lymphocytes exhibited increased tumor necrosis factor production, while the abundance of exhausted T lymphocytes was decreased." (PMID 37894446, 2023). "Podoplanin (PDPN) is known to be upregulated in tumor cells, tumor‐associated fibroblasts and inflammatory macrophages." (PMID 37434432, 2023). "External cohort of 95 GBM patients by immunohistochemistry (IHC) assay demonstrated that ANXA1, COL6A1, and PDPN were significantly upregulated in tumor tissues of high‐risk GBM patients." (PMID 37434432, 2023). "Correlation analysis together with verification in vitro suggested PDPN highly positively relevant tumor-associated neutrophils (TANs) and tumor-associated macrophages (TAMs)." (PMID 36434176, 2023). "The literature showed that PDPN is a stably expressed gene in tumour-associated fibroblasts and regulates the release of TGF-β through a positive feedback mechanism." (PMID 36653841, 2023). "The pathological involvement of PDPN has often been linked to cancer due to its expression on tumor cells, CAFs, or tumor-associated macrophages, which correlates with a poor prognosis." (PMID 37809094, 2023). "This is particularly important when PDPN is expressed by cancer cells, as it is actually associated with more aggressive tumor phenotypes." (PMID 37298679, 2023). "PDPN is a transmembrane mucin receptor that has been identified as a tumor promotor expressed by a variety of cancers and associated CAFs." (PMID 35177067, 2022). "Clonogenic assays and xenograft experiments revealed that PDPN expression was associated with radiotherapy resistance and tumor aggressiveness." (PMID 36059614, 2022). "Podoplanin is upregulated in cancer-associated fibroblasts (CAFs) and immune cells of tumor stroma in adenocarcinoma and colorectal cancer." (PMID 35936717, 2022). "There was a significant statistical association between tumor grade and podoplanin reactivity which was consistent with other studies." (PMID 36247509, 2022). "PDPN+ cells found to be infiltrating tumour regions were associated with worse survival.Tumours with less PDPN+ CAFs were likely to have a better response to chemotherapy." (PMID 36313650, 2022). "In stage I LUSC, the number of stromal CD204+ tumor-associated macrophages (TAMs) was reported to be significantly higher in patients with PDPN+ CAFs than in those with PDPN− CAFs." (PMID 36422541, 2022). "The 237mAb was revealed to detect a glycopeptide of the PDPN extracellular domain that was produced as a result of a tumor-specific mutation in the Cosmc gene that abolished the enzyme core 1 β1,3-galactosyltransferase." (PMID 35159384, 2022). "In our analysis, we found significant results for both Ki-67 and Picoplatin expression in association with histopathological tumor grade (podoplanin p = 0.0378; Ki-67 p = 0.0503)." (PMID 36077194, 2022). "In patients with large tumor or solid tumor metastases, PDPN expression induced poor prognosis in cancer-associated fibrous tissue." (PMID 36276279, 2022). "PDPN-positive CAF cases display high CD204+ tumor-associated macrophage (TAM) levels and a low CD8/FOXP3 T cell ratio." (PMID 35159384, 2022). "First, we demonstrated that PDPN expressed by activated CAFs in the tumor is linked to poor prognosis." (PMID 34879110, 2021).